PPP2R5B (protein phosphatase 2 regulatory subunit B'beta)
Description:
As the regulatory component of the serine/threonine-protein phosphatase 2A (PP2A) holoenzyme, modulates substrate specificity, subcellular localization, and responsiveness to phosphorylation. The phosphorylated form mediates the interaction between PP2A and AKT1, leading to AKT1 dephosphorylation.
Synonyms: FLJ35411; B56B; PR61B; B56beta
Tractability: PROTAC: UniProt records ubiquitination sites on it; ubiquitination databases record sites on it; its protein half-life has been measured.
Gene: Protein-coding gene on chromosome 11 (64,917,553 to 64,934,480, forward strand). Ensembl gene ENSG00000068971.
Subcellular location: Cytoplasm
Pathways (Reactome):
Disease: APC truncation mutants have impaired AXIN binding; AXIN missense mutants destabilize the destruction complex; CTNNB1 S33 mutants aren't phosphorylated; CTNNB1 S37 mutants aren't phosphorylated; CTNNB1 S45 mutants aren't phosphorylated; CTNNB1 T41 mutants aren't phosphorylated; Signaling by GSK3beta mutants; Truncations of AMER1 destabilize the destruction complex
Signal Transduction: Beta-catenin phosphorylation cascade; Degradation of beta-catenin by the destruction complex; Disassembly of the destruction complex and recruitment of AXIN to the membrane; Negative regulation of MAPK pathway; PI5P, PP2A and IER3 Regulate PI3K/AKT Signaling; RAF activation; RHO GTPases Activate Formins
Cell Cycle: Amplification of signal from unattached kinetochores via a MAD2 inhibitory signal; EML4 and NUDC in mitotic spindle formation; Mitotic Prometaphase; Resolution of Sister Chromatid Cohesion; Separation of Sister Chromatids
Immune System: Co-inhibition by CTLA4; Co-stimulation by CD28
Cellular responses to stimuli: XBP1(S) activates chaperone genes
Hemostasis: Platelet sensitization by LDL
Gene Ontology:
Molecular function: protein binding; protein phosphatase activator activity; protein phosphatase regulator activity
Biological process: signal transduction
Cellular component: protein phosphatase type 2A complex; cytoplasm; cytosol; nucleus
Genetic constraint (gnomAD): Loss-of-function variants: 19 observed, 57.43 expected, observed/expected ratio (o/e) 0.33, 90% interval 0.23 to 0.49. The upper end of that interval is the gene's LOEUF score, 0.49, which puts it in group 2 of 6, group 1 being the genes least tolerant of losing a copy. Missense variants: 418 observed, 626.9 expected, observed/expected ratio (o/e) 0.67, 90% interval 0.62 to 0.72. Synonymous variants: 276 observed, 257.84 expected, observed/expected ratio (o/e) 1.07, 90% interval 0.97 to 1.18.
Homologues: Orthologues: chimpanzee PPP2R5B (99% identical), rat Ppp2r5b (99% identical), guinea pig PPP2R5B (99% identical), mouse Ppp2r5b (99% identical), pig PPP2R5B (99% identical), macaque PPP2R5B (99% identical), dog PPP2R5B (94% identical), rabbit PPP2R5B (82% identical), tropical clawed frog ppp2r5b (81% identical), zebrafish ppp2r5b (80% identical), Drosophila melanogaster wdb (63% identical), Caenorhabditis elegans pptr-1 (61% identical), and 1 more. Paralogues in human: PPP2R5A (68% identical), PPP2R5E (67% identical), PPP2R5D (62% identical), PPP2R5C (61% identical).
Diseases named in the same sentence as PPP2R5B in open-access papers:
PPP2R5B is named in the same sentence as 11 diseases in open-access papers, as found by Europe PMC text mining. Sharing a sentence is not in itself a finding about the gene and the disease. The quoted sentences say what the papers report.
liver cancer (3 papers, 2021 to 2023). An epithelial or non-epithelial malignant neoplasm that arises from the liver. "The gene DDX11 has mutations in 5 liver cancer samples, while PPP2R5B has mutations in 3 samples." (PMID 34094926, 2021).
Insulin resistance (2 papers, 2017 to 2023). Increased resistance towards insulin, that is, diminished effectiveness of insulin in reducing blood glucose levels. "PPP2R5B is a subunit encoding protein phosphatase 2A (PP2A), which is associated with insulin resistance.PP2A is widely recognized as a tumor suppressor, studies have shown that low expression of PPP2R5B improves survival." (PMID 37415742, 2023).
Intellectual disability (2 papers, 2015 to 2025). "Because mutations in multiple subunits, including PPP2R1A, PPP2R5B, PPP2R5C, and PPP2R5D, have been linked to intellectual disability, future studies will investigate their roles in eCB signaling and related neuropsychiatric disorders." (PMID 40839403, 2025). "We have identified heterozygous missense mutations in PP2A regulatory subunit B family genes PPP2R5B, PPP2R5C and PPP2R5D in individuals with overgrowth and intellectual disability." (PMID 25972378, 2015).
cervical cancer (1 paper, 2021). A primary or metastatic malignant neoplasm involving the cervix. "It has been reported that deleted PPP2R5B gene induced sensitivity to paclitaxel in cervical cancer, and this sensitivity change was supposed to be associated with apoptosis." (PMID 33712023, 2021).
hepatocellular carcinoma (1 paper, 2024). A malignant tumor that arises from hepatocytes. "According to previous reports, PPP2R5B, and EFNA2 can be used as a prognostic biomarker for hepatocellular carcinoma." (PMID 39671369, 2024).
otosclerosis (1 paper, 2018). Formation of spongy bone in the labyrinth capsule which can progress toward the stapes (stapedial fixation) or anteriorly toward the cochlea leading to conductive, sensorineural, or mixed hearing loss. "Here, we genotyped eight previously associated variants in the following six candidate genes: RELN, BMP2, FGF2, COL1A1, TGFB1, and PPP2R5B in a large UK case–control otosclerosis cohort (n = 748)." (PMID 29728750, 2018).
tumor (7 papers, 2015 to 2024). "Risk scores were correlated with tumor stage; BMF was associated with age, gender, grade, and stage; PPP2R5B and LGALS3 were correlated with stage; SQSTM1 was associated with age and gender; while TOP2A was correlated with grade and stage." (PMID 33712023, 2021). "Furthermore, higher expression levels of ATF3, PPP1R15A, PPP2R5B, DDIT3, and BCL10 are associated with better prognosis in HER2+-BC patients, suggesting an overall tumor-suppressive role of the UPR-driven signaling cascade." (PMID 34007022, 2021). "For example, within the 3D structure of PPP2R5B protein generated by AlphaFold 2, we identified an intra-protein 3D cluster composed exclusively of rarely mutated residues (i.e., mutated in no more than two tumor samples)." (PMID 36945530, 2024). "The results revealed that the expression of prognostic genes was significantly higher in tumor grades 3–4 than in tumor grades 1–2, except for POLR2L and PPP2R5B (P < 0.05)." (PMID 37923899, 2023). "As PP2A is generally recognized as a tumor suppressor, studies have shown that highly expressed mitotic regulators and low-expressed PP2A class I subunits (such as PPP2R5B) can improve survival rate." (PMID 34094926, 2021). "The mechanism of action of PPP2R5B in HCC is still unclear.HSP90AA1 belongs to the heat shock protein (HSP90) family, and many of its regulated client proteins are proto-oncogene products or important signal transduction factors in tumorigenesis and are closely related to tumor development." (PMID 37415742, 2023).
cancer (3 papers, 2017 to 2023). A tumor composed of atypical neoplastic, often pleomorphic cells that invade other tissues. "On the other hand, elevated PPP2R5B expression has been found to be associated with increased drug sensitivity of cancer cells to several chemotherapeutic agents, including oxaliplatin." (PMID 37923899, 2023). "In this study, the effects of DAP3, GSDME, PLK1, and PPP2R5B knockdown on cancer cell growth were analyzed by DepMap, a cancer survival-dependent gene database." (PMID 37415742, 2023). "PPP2R5B and PPP2R2B belong to the protein phosphatase 2A family, which is implicated in the negative regulation of AKT protein, and consequently reduces cancer cell growth and division." (PMID 28114404, 2017). "Depmap database was used to explore genome-wide knockout library screening data, and pan-cancer analysis of DAP3, PPP2R5B, PLK1, and GSDME genes on cancer cell growth." (PMID 37415742, 2023).
PPP2R5B also shares sentences with these, for which no sentence is quoted: lung carcinoma (1 paper); ovarian carcinoma (1); spinocerebellar ataxia (1).